RBMX (RNA binding motif protein X-linked)
Diseases named in the same sentence as RBMX in open-access papers (continued):
Sharing a sentence is not in itself a finding about the gene and the disease.
tumor (continued). "We compared the correlation between the expression of RBMX in clinical factors stage, T, N, M stage in normal group and four neoplasm stages." (PMID 37194014, 2023). "The results showed conspicuously higher RBMX, FMR1 and IGF2BP1 expression in tumor tissues, especially RBMX." (PMID 37194014, 2023). "High expressions of AGTRAP, SH3KBP1, and RBMX were found in tumor tissues and correlated with a poor prognosis." (PMID 36338975, 2022). "On the other hand, owing to the fact that TF RBMX, a kind of tumor suppressor, loses its function, its low expression is related to a high fructose diet and the synthesis of cholesterol." (PMID 35164166, 2022). "In summary, the present study identifies a newly negative regulator of aerobic glycolysis, RBMX, which is significantly downregulated in BCa tissues, and was negatively correlated with tumor stage, histological grade and patient prognosis." (PMID 33564070, 2021). "RBMX inhibited BCa cell proliferation, colony formation, migration, and invasion in vitro and suppressed tumor growth and metastasis in vivo." (PMID 34804951, 2021). "RBMX has been proposed as a potential tumor suppressor in several cancer types, including oral squamous carcinoma and lung cancer." (PMID 34638274, 2021). "RBMX expression was negatively correlated with tumor stage, histological grade and poor patient prognosis." (PMID 33564070, 2021). "Functional assays demonstrated that RBMX inhibited BCa cell proliferation, colony formation, migration, and invasion in vitro and suppressed tumor growth and metastasis in vivo." (PMID 33564070, 2021). "RBMX’s role in m6A methylation may contribute to the dynamic regulation of oncogenic lncRNAs, thereby influencing tumor biology." (PMID 40692788, 2025). "Similarly, knockout of RBMX significantly increased the proportion of CD4+T cells in immune cells of subcutaneous tumor tissues." (PMID 40941025, 2025). "Notably, these findings indicate that elevated RBMX expression is closely linked to an immunosuppressive microenvironment, characterized by decreased CD8+T cell infiltration and increased tumor-associated macrophages." (PMID 40941025, 2025). "This process orchestrates the bidirectional regulation of tumor plasticity and the immunosuppressive microenvironment, providing a theoretical foundation for developing precision therapeutic strategies targeting the RBMX/TGF-β axis." (PMID 40692788, 2025). "The proportion of the cytotoxic molecules IFN-γ and Granzyme B in CD8+T cells was higher in the knockout group than in the control, suggesting that RBMX knockout in tumor cells may influence CD8+T cell activity via cellular interactions." (PMID 40941025, 2025). "Moreover, the upregulated of RBMX is associated with the lower OS rates in HCC patients, suggesting a potential tumor-promoting role of RBMX in HCC." (PMID 40084261, 2025). "RBMX acts as a tumor suppressor, inhibiting tumor cell growth, migration, and invasion." (PMID 38539439, 2024). "Based on this evidence, RBMX may affect the tumor microenvironment by regulating the interaction between malignant tumor cells and immune cells." (PMID 38214653, 2024). "Based on this evidence, RBMX might influence the infiltration of MDSC to promote tumor progression and suppress the sensitivity of cancer cells to ICI therapy." (PMID 38214653, 2024). "In this study, we aimed to identify RBMX as a tumor suppressor." (PMID 33564070, 2021). "RBMX has been identified as a suppressor gene that inhibits tumorigenesis and tumor progression." (PMID 33564070, 2021). "RBMX, also known as hnRNP G, was involved in various processes, like pre-mRNA splicing and posttranscriptional regulatory mechanism, which were related to several vital processes of tumor initiation, progression, and metastasis." (PMID 33029523, 2020). "Hence, it is possible that RBMX is a potential tumor suppressor." (PMID 37756323, 2023).
tumor (continued). "Therefore, the expression levels of 7 m6A regulators (METTL14, YTHDC2, FTO, ALKBH5, HNRNPA2B1, VIRMA, and RBMX) were lower in both the OC tissues and the high-stage group, indicating their potential function as tumor suppressors in OC tumorigenesis and development." (PMID 34631700, 2021). "Therefore, higher RBMX expression may be involved in the immune defense, immune surveillance, and immune clearance of tumor cells in the tumor microenvironment, thus affecting tumor progression." (PMID 38214653, 2024). "Nevertheless, immunofluorescence images obtained from the Human Protein Atlas revealed that the RBMX protein was initially localized in the nucleus of the MCF7 and U-2 OS tumor cell lines." (PMID 38214653, 2024). "In our patient cohort, SOCS5 and RBMX in 6 pairs of matched HCC and adjacent non-tumor frozen tissues were detected by Western blotting, and we observed that both SOCS5 and RBMX were significantly higher expressed in HCC tissues." (PMID 38429411, 2024). "However, some studies revealed that RBMX may act as a tumor repressor." (PMID 38214653, 2024). "After further screening, we evaluated the relationship between expression of FMR1, LRPPRC, RBMX, YTHDC2, IGF2BP1 and clinical parameters, including stage, T (tumor infiltrating), N (lymphatic metastasis) and M (distant metastasis) in CRC." (PMID 37194014, 2023). "We evaluated the relationship between expression patterns of RBMX, FMR1, LRPPRC, YTHDC2, IGF2BP1 and clinical parameters, including stage, T (tumor infiltration), N (lymphatic metastasis), M (distant metastasis) in CRC." (PMID 37194014, 2023). "AGTRAP1, ABCC5, SH3KBP1, and RBMX were upregulated, while PTGR1 was downregulated in tumor samples as compared to normal samples." (PMID 36338975, 2022). "We found that the expression of IGF2BP2, RBMX, and HNRNPC was correlated with various activated cancer-related pathways, providing insight into the molecular mechanisms related to tumor progression." (PMID 33816266, 2021). "Spliceosome (RBMX, SRSF3 and U2AF1) was observed as one of the representative events in tumor molecular machinery." (PMID 33261069, 2020). "However, the regulatory factors reported in these studies are inconsistent, and downstream targets of PRPF8, such as PIRH2, RBMX, and APC2, exhibit low reproducibility across different tumor types." (PMID 40136404, 2025). "There was a significant enhancement in the H2-K1 signaling pathway and a notable weakening of the THBS-1 signaling pathway between tumor cells and CD8+T cells following RBMX knockout; the expression of H2-K1 in tumor cells significantly increased, while the THBS-1 expression was decreased." (PMID 40941025, 2025). "The immunohistochemical staining showed that RBMX expression was elevated in metastatic and recurrent tumor tissues compared to non-metastatic and non-recurrent cases." (PMID 40941025, 2025). "In addition, the m6A readers, including YTHDF1/2/3, HNRNPC, HNRNPA2B1, RBMX, PRRC2A, and CPSF6, also demonstrated a higher expression in the tumor samples compared to the normal tissues." (PMID 38610981, 2024). "FTO, RBMX, METTL3, and METTL14, have been demonstrated to be tumor proto-oncogenes or biomarkers through m6A, with METTL3 serving as a pathological diagnostic index and potential therapeutic target for ESCA, and with RBMX encoding HNRNPG to affect m6A, also a member of the hnRNPs family." (PMID 36195940, 2022). "Additionally, IGFBP5, RBMX and TAGLN2, had consistently investigations in peers’ mechanical studies that the three genes were upregulated and promoted tumor metastasis." (PMID 34446747, 2021). "However, unpaired T-tests results showed that RBMX and LRPPRC were significantly up-regulated in tumor tissues compared with normal tissues." (PMID 34149792, 2021). "Thus, we extracted data from The Cancer Genome Atlas (TCGA) and Genotype-Tissue Expression (GTEx) databases, and compared the RBMX transcriptional expression levels between the tumor and normal samples." (PMID 38214653, 2024).
tumor (continued). "By pair-wise Pearson correlation analysis using GEPIA website tool with tumor data from TCGA database, we found that the mRNA expression level of ZCCHC8 is positively correlate with RBMX level, suggesting that RBMX might regulate TERRA degradation by interacting with ZCCHC8." (PMID 37756323, 2023). "The compared with adjacent non-tumorous tissues, we found a higher level of RBM15, IGFBP1, RBMX, FTO, and ALKBH5 in all five STAD tissues, RBM15, FTO and ALKBH5 were overexpressed in STAD tumor tissues, while the expression of IGFBP1, RBMX was not changed in STAD tumor tissues." (PMID 37019148, 2023).
cancer (30 papers, 2015 to 2025). A tumor composed of atypical neoplastic, often pleomorphic cells that invade other tissues. "Subsequently, we performed immune cell infiltration analysis/immune regulator correlation analysis and ICI response analysis to examine the cell infiltration associations and the predictive effect of RBMX in cancer immunotherapy response, respectively." (PMID 38214653, 2024). "Analysis of immune cell infiltration in the pan-cancer setting was conducted to further assess the association between RBMX and cancer immunity using Spearman correlation analysis." (PMID 38214653, 2024). "This study presents the aberrant expression levels, single-cell distributions, effective prognostic roles, immune cell infiltration associations, and immunotherapy responses of RBMX as a biomarker in various types of cancer." (PMID 38214653, 2024). "RNA binding motif protein X-linked (RBMX) is a nuclear RNA-binding protein, associated with certain types of cancer by participating in the integration of sister chromatids and a combination of ribonucleoprotein complexes." (PMID 38214653, 2024). "Former studies indicated an opposite association of RBMX expression levels and prognosis in different cancer types." (PMID 34638274, 2021). "A network analysis of gene expression data taken from thousands of tumors indicated that RBMX is a key switch that is closely linked to important cancer drivers." (PMID 33564070, 2021). "Several lines of evidence have indicated that low levels of RBMX expression are associated with poor survival in people with one of various cancers." (PMID 33564070, 2021). "Moreover, we applied single-cell RNA landscape analysis, prognostic analysis, and gene set enrichment analysis (GSEA) to unveil the potential clinical usage and explore the underlying biological functions of RBMX in different cancer types." (PMID 38214653, 2024). "The results consistently showed that RBMX was closely associated with the prognosis of cancer." (PMID 38214653, 2024). "Future investigations should examine the mechanistic pathways by which RBMX influences alternative splicing and m6A modification across a broader range of cancers." (PMID 40692788, 2025). "The infiltration levels of progenitor cells and MDSC were positively correlated with RBMX in most TCGA cancer types." (PMID 38214653, 2024). "Across all cancer types, RBMX expression was most significantly upregulated in CHOL compared with normal tissues." (PMID 38214653, 2024). "We sought to gain insight into the role of RBMX in the biological processes of various types of cancer." (PMID 38214653, 2024). "The correlations between RBMX and immune regulators in the pan-cancer setting are illustrated in a heatmap." (PMID 38214653, 2024). "In this study, we initially analyzed the transcriptional expression levels, genomic alterations, copy number variations, and DNA methylations of RBMX across different types of cancer using datasets from public databases." (PMID 38214653, 2024). "RBMX prevents the formation of a specific cancer-promoting PKM isoform (Pyruvate Kinase M2 or PKM2), reducing cancer aggressiveness and glycolysis." (PMID 38539439, 2024). "Several studies have shown that the RBMX gene is a tumor suppressor in many cancers, including endometrial cancer and papillary thyroid cancer." (PMID 39366930, 2024). "We sought to further explore the predictive role of RBMX for the efficacy of immunotherapy in the pan-cancer setting." (PMID 38214653, 2024). "In the present study, we performed a comprehensive analysis of RBMX in the pan-cancer setting, and verified its effective role in the prediction of immunotherapy response." (PMID 38214653, 2024). "Altogether, these findings uncover a new role of RBMX in TERRA expression regulation and telomere integrity maintenance, and raising RBMX as a potential target of cancer therapy." (PMID 37756323, 2023).
cancer (continued). "In our study, 6 hnRNP proteins were found to interact with RBMX protein, suggesting that RBMX inhibited cancer progression by participating in the regulation of RNA splicing and processing." (PMID 33564070, 2021). "Twenty-two out of 1884 (1.1%) were chr.5q differentially expressed cancer-associated genes significantly up-regulated in BRAFV600E-PTC compared to BRAFWT-PTC and co-expressed with RBMX." (PMID 29156680, 2017). "Initially, we sought to determine the role of RBMX in various types of cancer." (PMID 38214653, 2024). "Moreover, immune cell infiltration analysis revealed that the infiltration levels of progenitor cells and MDSC were positively related to RBMX expression in most cancer types." (PMID 38214653, 2024). "Furthermore, our results provided clues for further investigating the involvement of RBMX in cancer progression and immunotherapy." (PMID 38214653, 2024). "Next, we conducted single-cell analysis for the expression of RBMX in the pan-cancer setting." (PMID 38214653, 2024). "Thus, RBMX plays critical roles in neurodegenerative diseases, cancer, and neuronal development, making it a potential target for disease prognosis and therapeutic intervention." (PMID 38539439, 2024). "Recently, numerous research studies revealed the role of RBMX in cancer progression." (PMID 38214653, 2024). "Moreover, RBMX was significantly positively associated with CD200, CD276, and butyrophilin like 2 (BTNL2) expression in most types of cancer." (PMID 38214653, 2024). "According to these data, RBMX may act as an immune-related RNA-binding protein-coding gene in numerous types of cancer." (PMID 38214653, 2024). "Therefore, we conducted GSEA to distinguish the cancer hallmarks of RBMX based on differentially expressed genes (DEGs) between the low- and high-RBMX subgroups in 33 types of cancer." (PMID 38214653, 2024). "Our results suggested that upregulated RBMX expression may affect the occurrence, prognosis, and treatment of cancer, and it is highly correlated with infiltrating MDSC." (PMID 38214653, 2024). "The analysis revealed that RBMX is highly expressed in most cancer types." (PMID 38214653, 2024). "In addition, m6A‐recruited the binding proteins, YTHDC1, YTHDC2, YTHDF3, and FMR1 were inversely correlated, while HNRNPC, HNRNPA2B1, YTHDF1, and RBMX positively correlated TSs in most cancer types." (PMID 36239411, 2023). "Actually, there are several lines of evidence implicating the role of RBMX in cancer." (PMID 37756323, 2023). "Surprisingly and intriguingly, we discovered that RBMX protein mainly interacts with RNA-binding proteins, indicating that it may play an important role in cancer progression by regulating RNA splicing and processing." (PMID 33564070, 2021). "In the future, targeting of RBMX may be a novel method in cancer therapy." (PMID 38214653, 2024). "Consequently, we assessed the predictive role of RBMX in cancer patients treated with ICIs." (PMID 38214653, 2024). "Finally, we indicated that RBMX may play an immunoregulatory role in cancer progression, affecting the therapeutic effects of immune checkpoint inhibitors in patients with cancer." (PMID 38214653, 2024). "Moreover, it validates the aberrant expression of RBMX in clinical cancer samples." (PMID 38214653, 2024). "To better understand the mechanisms underlying the association of NUSAP1 overexpression and cancer aggressiveness, we used AP–MS to identify novel interactions between NUSAP1 and several proteins with described functions in R-loop biology and DDR, including DHX9, ILF2, HNRPC, FUS, and RBMX." (PMID 37047232, 2023). "However, reports of RBMX expression levels in cancer samples are more contradictory." (PMID 34638274, 2021). "RBMX elicits gene regulatory networks with cancer-associated genes of chromosome 5q but not of 5p." (PMID 29156680, 2017).
cancer (continued). "Importantly, 9/22 (41%) of cancer-associated up-regulated genes on chromosome 5q significantly (p < 0.05) interacted with RBMX gene, whereas none of the cancer genes on 5p interacted with RBMX, indicating network specificity." (PMID 29156680, 2017). "Moreover, since our findings showed amplification of chromosome 5 we built RBMX and RBM10 gene regulatory network specifically with the cancer-associated genes located on chromosome 5p (33 genes) and 5q (68 genes) in BRAFV600E-PTC compared to BRAFWT-PTC TCGA samples." (PMID 29156680, 2017). "The RNA-binding motif protein X (RBMX), as an important RBP, has been reported to have a pro-cancer effect in various cancers." (PMID 40941025, 2025). "The wound healing assay demonstrated that RBMX knockdown significantly diminished the wound closure ability of ESCC cells, underscoring its role in cell migration, which is crucial for cancer invasion and metastasis." (PMID 40692788, 2025). "We examined the correlations between RBMX expression and TMB, as well as MIS with deep insight across various types of cancer." (PMID 38214653, 2024). "However, the specific role of RBMX in cancer immunity remains unknown." (PMID 38214653, 2024). "Our data point to a completely new role of RBMX in TERRA expression regulation and telomere integrity maintenance, and open up a potential way for cancer therapy." (PMID 37756323, 2023). "Using our algorithm, we also observed the over-representation of the binding sites of RBMX, SFRS1 and ELAVL1 in the set of enriched exosomal lncRNAs in cancer cell lines and in the healthy cells." (PMID 27102850, 2016). "Additionally, RNA modification genes, such as RBMX, HNRNPC, ALKBH5, and WTAP, play a crucial role in cancer biology." (PMID 38055673, 2023). "One gene found to interact with RBMX was methyltransferase-like 3 (METTL3), an oncogene that could promote translation of cancer cell proteins." (PMID 36077923, 2022). "We did not identify any RBP which uniquely target either the exosomal or the cellular lncRNAs, however there is a significant difference in the number of binding sites for RBMX, ELAVL1 and SFRS1 in the exosomal lncRNAs compared to cellular lncRNAs of both healthy and cancer cell lines." (PMID 27102850, 2016). "Using a set of 19 lncRNAs which were common to all cancer cell lines but not enriched in exosomes, we found a significant reduction (p value = 0.001) in enriched binding sites for both RBMX and ELAVL1." (PMID 27102850, 2016). "However, a comprehensive pan-cancer analysis of the role of RBMX has not been conducted thus far, and its functions in cancer immunity have not been described." (PMID 38214653, 2024). "Moreover, with the low expression of TF RBMX, it could upregulate miRNA MIR222 for the purpose of downregulating the downstream target genes DIRAS3 and DCTN6, enhancing cancer cell proliferation, cell survival rate, and inducing invasion." (PMID 35164166, 2022). "RBMX (RNA Binding Motif Protein X-Linked), NONO (Non-POU Domain Containing Octamer Binding) and FUS (FUS RNA Binding Protein) are the three RNA-binding proteins that have been demonstrated to be potential cancer drivers." (PMID 33202812, 2020). "In a recent report, the Ser216 residue of RBMX was identified as a phosphorylation substrate for TGF-β activated kinase 1 (TAK1), however, its precise role in cancer has not been reported." (PMID 39366930, 2024).